RN7SL285P (RNA, 7SL, cytoplasmic 285, pseudogene)
Gene: Miscellaneous RNA gene on chromosome 6 (37,832,922 to 37,833,185, reverse strand). Ensembl gene ENSG00000243313.
Homologues: Orthologues: chimpanzee Metazoa_SRP (98% identical), macaque Metazoa_SRP (75% identical). Paralogues in human: RN7SL2 (80% identical), RN7SL1 (80% identical), RN7SL672P (78% identical), RN7SL3 (77% identical), RN7SL50P (77% identical), RN7SL543P (77% identical), RN7SL660P (77% identical), RN7SL732P (77% identical), RN7SL184P (77% identical), RN7SL300P (77% identical), RN7SL326P (77% identical), RN7SL712P (77% identical), and 703 more.